GIN1 (gypsy retrotransposon integrase 1)
Synonyms: GIN-1; TGIN1; ZH2C2; FLJ20125
Tractability: PROTAC: ubiquitination databases record sites on it.
Gene: Protein-coding gene on chromosome 5 (103,086,000 to 103,120,226, reverse strand). Ensembl gene ENSG00000145723.
Subcellular location (Human Protein Atlas): Nucleoli; Nucleoplasm
Gene Ontology:
Molecular function: nucleic acid binding
Biological process: DNA integration
Genetic constraint (gnomAD): Loss-of-function variants: 2 observed, 5.78 expected, observed/expected ratio (o/e) 0.35, 90% interval 0.14 to 1.09. That is too few expected variants to judge how well the gene tolerates losing a copy. Missense variants: 67 observed, 81.51 expected, observed/expected ratio (o/e) 0.82, 90% interval 0.67 to 1.01. Synonymous variants: 18 observed, 25.24 expected, observed/expected ratio (o/e) 0.71, 90% interval 0.49 to 1.06.
Homologues: Orthologues: chimpanzee GIN1 (99% identical), macaque GIN1 (98% identical), dog GIN1 (93% identical), pig GIN1 (92% identical), rabbit GIN1 (89% identical), guinea pig GIN1 (86% identical), mouse Gin1 (85% identical), rat Gin1 (83% identical).
Diseases named in the same sentence as GIN1 in open-access papers:
GIN1 is named in the same sentence as 2 diseases in open-access papers, as found by Europe PMC text mining. Sharing a sentence is not in itself a finding about the gene and the disease. The quoted sentences say what the papers report.
Obesity (1 paper, 2023). Accumulation of substantial excess body fat. "While the eGenes, PAM, GIN1, and PPIP5K2, have not been studied in the context of obesity and metabolism, they have been studied for their function in other cell types." (PMID 37326626, 2023).
GIN1 also shares sentences with these, for which no sentence is quoted: Abdominal obesity (1 paper).